HIF1A (hypoxia inducible factor 1 subunit alpha)
Diseases named in the same sentence as HIF1A in open-access papers (continued):
Sharing a sentence is not in itself a finding about the gene and the disease.
gastric cancer (continued). "Contrary to the positive regulatory role of HIF-1α on CD44 and CD24, HIF-1α exhibited a negative regulatory effect on CD133 in a panel of gastric cancer cell lines." (PMID 36846589, 2023). "Overall, the downregulation of HIF-1α levels using IDF-11774 resulted in reduced viability, migration, and invasion of gastric cancer cells." (PMID 38140111, 2023). "In gastric cancer (GC), P4HB was found to exhibit a strong correlation with Hypoxia Inducible Factor-1α (HIF1α)." (PMID 38029391, 2023). "They observed that the expression of KLF8 increased substantially under hypoxic conditions in parallel to HIF-1α in MKN45, MKN28, and SGC7901 gastric cancer cells." (PMID 36846589, 2023). "In gastric carcinoma, RUNX3 binds to HIF-1α and PHD2, resulting in the hydroxylation of HIF-1α by PHD2, and subsequent ubiquitination of HIF-1α by VHL." (PMID 36899853, 2023). "In gastric cancer, P4HB was shown to play an important role in regulating invasion and migration in the HIF1α pathway." (PMID 35036081, 2022). "In one study, miR-301a-3p was upregulated both in hypoxic gastric cancer cells and exosomes released by these cells, and it was found to increase HIF-1α stability by targeting PHD3, forming a miR-301a-3p/PHD3/HIF-1α positive feedback loop." (PMID 35039054, 2022). "Crocin at 2–3 μM reduces the expression of HIF-1α in AGS and HGC-27 gastric cancer cells by inhibiting the miR-320/Krüppel-like factor 5 (KLF5)/HIF-1α signaling axis." (PMID 36438836, 2022). "Flavonoids: In gastric cancer cells (AGS), baicalein attenuated the expression of HIF-1α by regulating the PTEN/Akt/HIF-1α signaling pathway, inhibited the process of glycolysis in tumor cells, and reversed the hypoxia-induced 5-FU drug resistance." (PMID 36339566, 2022). "R8-modified vinorelbine combined with schisandrin B liposomes can significantly inhibit gastric cancer metastasis by downregulating VEGF, VE-Cad, HIF-1a, PI3K, MMP-2, and FAK." (PMID 36339625, 2022). "Crocin up-regulates the levels of miR-320, reduces the expression of KLF5, and reduces the levels of HIF-1α, thereby inhibiting the migration, invasion, and epithelial-mesenchymal transition (EMT) of gastric cancer cells." (PMID 36438836, 2022). "In gastric cancer cells, YY1 knockdown inhibited Wnt/β-catenin, JNK/MAPK, ERK/MAPK, ER, and HIF-1α signaling pathways." (PMID 35747809, 2022). "Furthermore, hypoxia-induced circNRIP1 enhances the resistance of gastric cancer (GC) to 5-FU by modulating HIF-1α-dependent glycolysis." (PMID 35915091, 2022). "Recent studies have demonstrated that HIF-1α promoted the proliferation, migration, invasion, angiogenesis and EMT in gastric cancer (GC) cells." (PMID 36033489, 2022). "The authors showed that binding of HIF1α and RON/β-catenin complexes are essential for gastric cancer cells to adapt to hypoxic conditions and acquire metastatic phenotypes." (PMID 35454943, 2022). "Taken together, this study shows that DS can interfere the expression of HIF-1α, thereby inhibiting TGF-β-mediated EMT of gastric cancer cells, and demonstrated a promising application of DS in gastric cancer therapy." (PMID 33976746, 2021). "On the one hand, it was shown to act as a competing endogenous RNA (ceRNA) for the miRNAs miR-186 and miR-199a-5p in gastric cancer and non-small cell lung cancer (NSCLC) cells, respectively, thereby preventing them from miRNA-mediated HIF-1α mRNA degradation." (PMID 32640630, 2020). "In gastric cancers, hypoxia induced BHLHE40 expression while the HIF-1α protein inhibitor decreased the expression of BHLHE40." (PMID 32577154, 2020). "Angiogenesis, manifested by upregulated HIF1A and VEGFA, is a part of the healing process of the gastric mucosa as well as a means of gastric cancer growth and dissemination." (PMID 32630408, 2020).
gastric cancer (continued). "For example, in human gastric cancer SGC7901 cells (in hypoxic state) EGCG (5, 10, 20, 40 μM), reduced expressions of HIF-1α (a subunit of a heterodimeric transcription factor hypoxia-inducible factor 1-HIF1) and VEGF with a concentration-dependent effect." (PMID 31979082, 2020). "For example, IL32 contributes to gastric cancer progression by increasing the metastatic potential resulting from AKT, β-catenin and HIF-1α activation." (PMID 32308549, 2020). "Previous study indicated that miR-520a-3p diminished gastric cancer cell glycolysis and proliferation by forming feedback with AKT1/mTOR/HIF1α pathway." (PMID 33768113, 2020). "We thus assayed the expression levels of HIF-1α and BCL-6 in gastric carcinoma cells transfected with PKM2 siRNA." (PMID 33376737, 2020). "We then observed the effects of inhibition and overexpression of HIF-1α and P4HB on invasion and metastasis in human gastric cancer cell lines." (PMID 31467922, 2019). "Immunohistochemistry was used to detect the expression of HIF-1α, NDRG2, E-cadherin, Snail and Twist in normal gastric tissues, gastric cancer tissues and lymph node metastasis." (PMID 33817155, 2019). "In this study, the expression of HIF-1α, NDRG2 and EMT-related proteins, including E-cadherin, Snail and Twist were evaluated in normal gastric tissues, gastric cancer tissues and lymph node metastasis tissues." (PMID 33817155, 2019). "It suppresses gastric carcinoma proliferation by inducing apoptosis in tumor cells, activating immune cells to release cytokines, and suppressing the STAT3, VEGF, HIF-1α, and DEC1 signaling transduction pathways." (PMID 30871059, 2019). "Immunohistochemistry showed co-localization of HIF-1α and TGF-β in gastric cancer, suggesting that HIF-1 combined with HREs also promote the expression of downstream TGF-β molecules in gastric cancer cells." (PMID 30477520, 2018). "Effects of HIF-1α siRNA silencing as well as PI3K activator sc3036 on proliferation, migration, and invasion of gastric cancer cells were detected by Cell counting kit (CCK-8) assay, and Transwell migration and invasion assay." (PMID 29899167, 2018). "However, Chen found metformin may inhibit gastric cancer by inhibiting HIF1α/PKM2 signaling." (PMID 28903449, 2017). "HIF-1α-inducible miR-382 promotes angiogenesis and acts as an oncogene by directly targeting PTEN in gastric cancer under hypoxia." (PMID 28173803, 2017). "To evaluate angiogenesis-related molecules and antiapoptosis molecule, GRP78, in gastric cancer, we first examined microvessel density (MVD; CD34), HIF-1α, VEGF, and GRP78 in 42 cases of gastric carcinoma." (PMID 29072683, 2017). "Under hypoxic conditions, the expression of AM, HIF-1α, NDRG3, and VEGFA are significantly elevated in the human gastric cancer cell line BGC-823." (PMID 29179449, 2017). "Overexpression of lncRNA PVT1 in gastric carcinoma promoted the development of multidrug resistance and influenced the expression of MDR-related proteins (MDR1, MRP1, mTOR, and HIF-1a)." (PMID 29046366, 2017). "Taken together, the comparative analysis of HIF-1α, ANXA1 and MYC expression in human gastric cancer samples confirmed the in vitro data, further indicating a potential functional association between HIF-1α, ANXA1 and MYC in this tumor entity." (PMID 26760764, 2016). "Induction of CoCl2 up regulated the expression of endogenous miR-421, while co-transfection of HIF-1α siRNA would down regulate the expression of miR-421 in turn in SGC-7901 and AGS gastric cancer cell lines." (PMID 27016414, 2016). "Recent research indicated that upregulation of PVT1 inhibited apoptosis in gastric cancer cell lines, increased the expression of MDR1, MRP, mTOR, and HIF‐1α, promoted the development of multidrug resistance." (PMID 27794184, 2016).
gastric cancer (continued). "To explore the contrasting uptake responses to the NIRF dye as exhibited by gastric tumor and ulcer tissues, we analyzed HIF1α and OATP1B3 expression, which are considered to increase dye uptake in gastric cancer cells, in different tissue samples." (PMID 27329598, 2016). "Small interfering RNA (siRNA) against HIF-1α and HIF-2α in gastric cancer cells significantly inhibited hypoxia-induced adhesive and invasive abilities." (PMID 25590810, 2015). "A previous study by our group indicated that hypoxia is able to increase HIF-1α expression, which upregulates MMP-9 and uPA receptor expression in gastric cancer cells, resulting in increased adhesion, migration and invasion." (PMID 25997455, 2015). "This study aimed to determine the correlation between HIF-1α and miR-27a expression and to evaluate the effect of inhibition of HIF-1α expression on miR-27a expression and drug resistance in gastric cancer (GC)." (PMID 26292288, 2015). "In accordance with this finding, another MEK1/2 inhibitor U0126 was able to decrease the expression of HIF-1α protein and the paracrine secretion of VEGF in SGC7901 gastric cancer cells." (PMID 26567773, 2015). "Real-Time PCR and western blot showed increasing of HIF-1α in mRNA and protein levels as well as TIMP1, TFF3 in mRNA levels in gastric cancer tissues." (PMID 24927122, 2014). "Most studies have shown a correlation between CD133 expression and HIF-1α expression, but interestingly, downregulation of CD133 expression by HIF-1α expression in a gastric cancer cell line has also been reported." (PMID 23558457, 2014). "In this study, the correlations of TGF-β, HIF-1α, VEGF and pERK1/2 expressions with clinicopathologic parameters and prognosis were evaluated in patients with gastric cancer." (PMID 24614305, 2014). "Hypoxia-inducible factor 1-alpha (HIF-1α), the key transcription factor, plays an important role in gastric cancer development and progression." (PMID 24927122, 2014). "The aim of this study was to clarify the clinical role of CD133 expression in gastric cancer and to investigate the correlation between CD133 expression and HIF-1α expression." (PMID 23558457, 2014). "Among the total of 446 gastric cancer specimens, TGF-β overexpression was detected in 181 (40.6%), HIF-1α overexpression in 217 (48.7%), VEGF overexpression in 194 (43.5%), and pERK overexpression in 149 (34.3%)." (PMID 24614305, 2014). "From a recent meta-analysis, increased HIF-1α and aberrant expression of PTEN can be used to predict the prognosis of gastric cancer." (PMID 24914051, 2014). "In the future, some drug therapies targeting HIF-1α itself or HIF-1α mediated cascades such as glucose metabolism, carcinogenesis, angiogenesis, invasion, metastasis, apoptosis and chemoresistance might be designed, thereby improving unfavorable outcomes in gastric cancer patients." (PMID 24216696, 2013). "Previously, our group has found that RhoE was enhanced in gastric cancer cells by induction of HIF-1α expression under hypoxic conditions and promoted EMT of gastric cancer cells." (PMID 24312338, 2013). "We previously established two gastric cancer cell lines with HIF-1α knockdown (KD), MKN45-KD and MKN74-KD, and demonstrated the involvement of HIF-1α expression in chemoresistance using nude mouse xenograft models." (PMID 23181099, 2012). "In our experiments, levels of both HIF-1α and NF-κB were reduced in nuclei upon GLO1 silencing in gastric cancer cell lines, along with downstream target genes (VEGF, CXCL1, CXCL8, MMPs)." (PMID 22479608, 2012). "The seven RNAs upregulated in gastric cancer were CLDN18, EPCAM, REG4, BBC3, OLFM4, PPARG, and CDH17, while the two downregulated genes were IFITM1 and HIF1A." (PMID 22929309, 2012). "To investigate the role of HIF-1α in gastric tumour growth derived from SNU gastric cancer cells, we blocked the HIF-1α pathway in three gastric cancer cell lines using shRNA expression." (PMID 21119667, 2011).
gastric cancer (continued). "Previously, it was found that HIF-1α activation was significantly correlated with VEGF protein expression, and this overexpression was a prognostic factor in patients with gastric cancer." (PMID 21119667, 2011). "In the present study, through a cell culture system, we found that hypoxia was involved in the NF-κB effect on the expressions of HIF-1α protein and VEGF mRNA in gastric cancer cells." (PMID 21119667, 2011). "The hypoxia-dependent activation of the NF-κB/HIF-1α/VEGF pathway contributes, at least in part, to gastric cancer promotion via enhancement of angiogenesis." (PMID 21119667, 2011). "Our results showed that shRNA-mediated downregulation of HIF-1α expression reduced the cell viability of SNU-668, SNU-484, and SNU-216 gastric cancer cells in vitro under hypoxic conditions." (PMID 21119667, 2011). "Thus, we investigated whether HIF-1α mediates the role of NF-κB in gastric cancer angiogenesis." (PMID 21119667, 2011). "To remove the possible confounding effects of HIF-1α and VEGF on the relationship between cytoplasmic pFOXO1 expression and angiogenesis in gastric cancer, we divided samples into two groups according to the expression of HIF-1α or VEGF." (PMID 21696576, 2011). "However, in our experiments we could neither show lowered ATP levels in HIF-1α-deficient gastric cancer cells nor did addition of excess free ATP rescue the motility of HIF-1α-deficient cells (data not shown)." (PMID 19223895, 2009). "Human gastric cancer cells AGS and MKN28 were transduced with lentiviral vectors containing the H1 promoter-driven human HIF-1α siRNA (knockdown, ‘KD’) or unspecific control siRNA (scrambled, ‘SCR’)." (PMID 19223895, 2009). "Functional inactivation of HIF-1α resulted in a significantly reduced ability of AGS and MKN28 gastric cancer cells to migrate and to invade an artificial basal membrane under normoxic as well as hypoxic conditions." (PMID 19223895, 2009). "Notably, knockdown of B7H3 in gastric cancer cells significantly inhibited both the expression and nuclear localization of HIF-1α, whereas overexpression of B7H3 markedly promoted HIF-1α expression." (PMID 41710663, 2026). "The transcription factor hypoxia-inducible factor-1α (HIF-1α) orchestrates angiogenesis, metabolic rewiring, extracellular matrix (ECM) remodeling, and immune evasion, and high HIF-1α expression in gastric cancer correlates with greater microvessel density, nodal metastasis, and advanced stage." (PMID 41373680, 2025). "Exposure of gastric cancer cell lines (BGC-823, HGC-27, and SGC-7901) to hypoxia (1% O2) or chemical hypoxia induced by CoCl2 markedly increases CD73 (ecto-5′-nucleotidase) expression through HIF-1α-dependent transcriptional activation." (PMID 41441084, 2025). "Therefore, activation of the NF-κB/HIF-1α/VEGF pathway exhibits hypoxia-dependent nature and contributes to the promotion of angiogenesis in gastric cancer." (PMID 39370481, 2025). "Furthermore, ChIP and luciferase assays demonstrated that HIF-1α binds to the promoter region of lncRNA HYPAL, thereby promoting its expression in gastric cancer cells." (PMID 40861273, 2025). "Both HIF-1α and Foxp3 levels were higher in advanced metastatic gastric cancer tissues than in nonmetastatic gastric cancer tissues." (PMID 40216744, 2025). "Also, Vitexin inhibited the gastric cancer in vivo and vitro by suppressing HMGB1-mediated activation of PI3K/Akt/HIF-1α signaling pathway." (PMID 41351800, 2025).
gastric cancer (continued). "Furthermore, the prognostic models constructed by the carcinogenic genes JUN, HIF1A, and PTGS2 are significantly correlated with the survival time of gastric cancer patients." (PMID 40391580, 2025). "Additionally, it will be important to investigate the combined effects of HIF‐1α, a VHL target, and SYT11 on the growth, migration, and invasion of gastric cancer cells following VHL inhibition." (PMID 40576306, 2025). "Collectively, these compelling findings underscore the pivotal role of the JUN, HIF1A, and PTGS2 genes as promising clinical prognostic markers for patients grappling with gastric cancer, heralding a paradigm shift in personalized prognostication strategies within the oncological landscape." (PMID 40391580, 2025). "Additionally, both HIF-1α and lncRNA GAPLINC are upregulated in gastric cancer tissues and cell lines." (PMID 40861273, 2025). "Conversely, Helicobacter pylori (H. pylori) infection, which promotes the generation of proinflammatory interleukins, significantly upregulates AQP3 expression by stimulating HIF-1α and ROS in gastric cells, linking H. pylori infection to increased AQP3 expression and gastric cancer development." (PMID 39857360, 2024). "Additionally, YBX1 induces aerobic glycolysis by activating protein expression of HIF-1α and MYC in gastric cancer cells 46-48." (PMID 38948065, 2024). "However, another study on gastric cancer demonstrated that crocin inhibits the EMT, migration and invasion of cancer cells obtained from biopsies of gastric cancer patients, through the miR-320/Krüppel-like factor 5 (KLF5)/HIF-1α signalling pathway." (PMID 39334719, 2024). "In gastric cancer, targeting the PI3K/AKT pathway may be useful to suppress HIF-1α or improve the effectiveness of HIF-1α inhibitors." (PMID 39816318, 2024). "Additionally, Toosendanin, an extract from Chuanlianzi, downregulates STAT3 expression, inhibiting HIF-1α activity and thus attenuating AEG in gastric cancer cells." (PMID 39906672, 2024). "Therefore, targeting HIF-1α’s transcription, translation, and expression becomes a vital strategy for controlling AEG and halting gastric cancer progression." (PMID 39906672, 2024). "By assessing the impact of IDF-11774 on gastric cancer cell proliferation, we observed a dose-dependent inhibition of MKN45 and MKN74 cell proliferation, particularly post-DMOG pre-incubation and HIF-1α overexpression." (PMID 38140111, 2023). "Therefore, the downregulation of HIF-1α expression via IDF-11774 induced cell cycle arrest and activated MAPK signaling, leading to the apoptosis of gastric cancer cells." (PMID 38140111, 2023). "Furthermore, crocin has been observed to modify the expression of Krüppel-like factor 5 (KLF5), hypoxia-inducible factor-1α (HIF-1α), and miR-320 in AGS and HGC-27 gastric cancer cells." (PMID 37736510, 2023). "Since rapamycin, which down-regulates HIF-1α, could revert these changes, HIF-1α was suggested as the mediator of CD44 induction and stemness in gastric cancer cells." (PMID 36846589, 2023). "Therefore, IDF-11774 successfully inhibited HIF-1α expression via the ubiquitin–proteasome system, even under hypoxic conditions, and promoted cytoplasmic degradation in HIF-1α of gastric cancer cells." (PMID 38140111, 2023). "First, we assessed the expression level of HIF-1α in two gastric cancer cell lines, MKN45 and MKN74, under normoxic and dimethyloxalylglycine (DMOG)-induced hypoxic conditions." (PMID 38140111, 2023).